ALB (albumin)
Diseases named in the same sentence as ALB in open-access papers (continued):
Sharing a sentence is not in itself a finding about the gene and the disease.
Hypoalbuminemia (continued). "At 23 months post-surgery, he showed no hypoalbuminemia, edema, or related symptoms; body weight and serum albumin remained normal." (PMID 41041446, 2025). "Patients with hypoalbuminemia (albumin < 3.0 g/dL) had a significantly prolonged ICU stay (median 71.0 vs. 60.5 h, p = 0.046) compared to patients with normal albumin levels (≥3.0 g/dL), reflecting a potential link between poor nutritional status and increased healthcare resource utilization." (PMID 41010314, 2025). "∆Alb was significantly associated with postoperative complications in patients with normal preoperative albumin levels (p < 0.001), but was not in patients with hypoalbuminemia (p = 0.808)." (PMID 40432957, 2025). "In a meta-analysis of cohort studies, the treatment of hypoalbuminemia through albumin administration did not lead to an overall reduction in morbidity." (PMID 40649163, 2025). "Our study demonstrated that 80.5% of AKI patients with hypoalbuminemia responded to FST without prior albumin infusion." (PMID 41291529, 2025). "Hypoalbuminemia <3.5 g/dL was found to increase odds of 30-day non-home discharge in multivariate analysis, and lower albumin level on a continuous scale was similarly found to be associated with greater odds of non-routine discharge in adjusted results." (PMID 40103850, 2025). "Incorporation of serum albumin and/or hypoalbuminemia into clinical outcome predictive models is not a novel phenomenon, as several of these prognostic indices already rely on patient albumin status to estimate survival and other measures of morbidity." (PMID 40103850, 2025). "The negative correlation with albumin aligns with the systemic involvement of the disease, as hypoalbuminemia is commonly observed in advanced disease stages and is associated with poor prognosis." (PMID 40369504, 2025). "Lastly, due to the absence of albumin records, serum AG was not corrected for albumin, despite some studies indicating that hypoalbuminemia affects serum AG concentrations." (PMID 40748976, 2025). "Data were extracted using a standardized form that captured study characteristics (first author, year, country, design, sample size), patient demographics, definitions of hypoalbuminemia, AKI diagnostic criteria, serum albumin values in AKI and non-AKI groups." (PMID 41523521, 2025). "Regardless of gender, the pre‐ and post‐surgical albumin in the AL group was significantly lower than those in the non‐AL group, and hypoalbuminemia as well as anemia were more common in the AL group." (PMID 40346009, 2025). "In the PL group, eight (23.53%) patients had hypoalbuminemia (serum albumin <30 g/L) compared with six (3.97%) patients in the non-PL group." (PMID 39896723, 2025). "Given this uncertainty, we do not recommend routine IV albumin infusion for hypoalbuminemia correction in calciphylaxis patients." (PMID 40600068, 2025). "Hypoalbuminemia can be considered a consequence of acute and/or chronic infection, considering that albumin is a negative acute-phase protein." (PMID 39997430, 2025). "Hypoalbuminemia would be expected in infected dogs as albumin is classified as a negative acute-phase protein." (PMID 40817086, 2025). "Our analysis revealed a decline in albumin as renal function declined, which was evident in both sexes, although the mean albumin levels did not drop below the cutoff value of 3.5 g/dl, which is commonly used to define hypoalbuminemia." (PMID 40384966, 2025). "One study utilized albumin as a dichotomous variable (normal vs. hypoalbuminemia) but did not define a cutoff value." (PMID 40103850, 2025). "With emerging evidence linking hypoalbuminemia to frailty, the prognostic significance of serum albumin levels should not be overlooked in geriatric populations." (PMID 41431585, 2025). "By contrast, mortality was not increased in patients with severe hypoalbuminemia, as indicated by albumin levels of 0.0–1.0 g/dL." (PMID 40649163, 2025).
Hypoalbuminemia (continued). "Among AP patients with hypoalbuminemia, there were significant amounts of non-esterified fatty acids that are not bound to albumin, leading to impaired immune cell function and an increased risk of infection and sepsis." (PMID 40773463, 2025). "Although serum albumin has not been considered an independent risk factor for the prognosis of women with AFLP, hypoalbuminemia was frequently observed in patients suffering from AFLP." (PMID 40529137, 2025). "Additionally, hypoalbuminemia common in cancer patients weakens hepatic antioxidant defenses, and the “inflammation-nutrition imbalance” marker NPAR (neutrophil percentage/serum albumin) demonstrates high efficiency in predicting ALI (AUC = 0.89–0.93)." (PMID 40963676, 2025). "Hypoalbuminemia may be caused by protein-losing nephropathy due to glomerulonephritis and acute renal injury subsequent to a B. gibsoni infection, or it can occur when there is a decrease in albumin production, a negative acute-phase protein, during systemic inflammatory response." (PMID 40075928, 2025). "Hypoalbuminemia in the postoperative period can be attributed to the acute-phase response, where albumin, a negative acute-phase reactant, decreases due to both increased capillary permeability and a reduction in hepatic synthesis." (PMID 41185828, 2025). "Since albumin levels were not routinely checked, the “Hypoalbuminemia (albumin < 3 mg/dL)” in the comorbidity was excluded from the scale." (PMID 40200564, 2025). "It is possible that ALB levels in this study focusing on healthy individuals were not affected because it did not include individuals with hypoalbuminemia." (PMID 41298696, 2025). "In-hospital mortality was similar regardless of admission ALB: patients with hypoalbuminemia on arrival had a mortality of ~14.2% versus 12.2% in normoalbuminemic patients (p = 0.71)." (PMID 41226896, 2025). "Albumin levels displayed a clear negative correlation: lower levels (blue) significantly increased SHAP values, indicating that hypoalbuminaemia markedly elevated predicted risk." (PMID 41551318, 2025). "∆Alb was significantly associated with postoperative complications in patients with normal preoperative albumin levels (AUC = 0.651, p < 0.001), but was not in patients with hypoalbuminemia (p = 0.808)." (PMID 40432957, 2025). "Albumin is thought to break up rouleaux and slow down red cell aggregation, resulting in a lower ESR and potentially explaining the correlation between clinical hypoalbuminemia and elevated ESR." (PMID 38560628, 2024). "However, hypoalbuminemia is commonly observed in NSCLC patients and those with hepatic impairment, leading to a decrease in albumin levels." (PMID 38500771, 2024). "Collectively, our research and that of others have consistently shown a marked decrease in blood albumin levels in patients who do not survive, suggesting that hypoalbuminemia is a critical factor in predicting mortality in pediatric septic shock." (PMID 39246646, 2024). "Albumin concentration in serum from Pcc-infected mice was reduced by ∼50% (i.e., hypoalbuminemia), compared with noninfected controls." (PMID 38307624, 2024). "The mean average albumin level for patients who experienced postoperative complications was 30.46 g/L, indicative of hypoalbuminemia, while patients without complications had a normal albumin level." (PMID 38707022, 2024). "As a negative acute phase reactant, albumin has an inverse relationship with oxidative stress and inflammation, the degree of hypoalbuminemia correlates with the intensity of the inflammatory response in critically ill patients." (PMID 38515077, 2024). "Similarly to other studies where hypoalbuminemia was correlated with AKI, the AKI patients in the analyzed group had lower albumin concentrations (2.7 ± 0.5 vs. 3.0 ± 0.6 [g/dL], p < 0.001) than NKF patients." (PMID 38592301, 2024).
Hypoalbuminemia (continued). "In our study, patient distribution into mGPS and GPS groups was identical as none of the hypoalbuminemia patients (i.e. albumin <35 g/L) had a CRP value <10 mg/L." (PMID 39691271, 2024). "In addition, hypoalbuminemia can inhibit renal 11β-HSD2 activity because of the low binding rate between glycyrrhizin metabolites and serum albumin." (PMID 38165850, 2024). "Hypoalbuminemia in NS is usually a result of extreme proteinuria and not of impaired albumin synthesis in the liver." (PMID 39245782, 2024). "Serum albumin also exhibited a significant difference between the groups; however, it is essential to highlight that none of the patients presented hypoalbuminemia (serum albumin <3.5 g/L) after a month of progression." (PMID 38674430, 2024). "The study even argues that interventions such as intravenous albumin infusion, aimed at correcting hypoalbuminemia, did not significantly alter the course of the patient's hospital stay." (PMID 38707022, 2024). "While the prevalence of hypoalbuminemia was not statistically different between patients who survived and those who did not, albumin levels were significantly lower in the patients who died during the study period." (PMID 38592101, 2024). "Huiting Xu and al demonstrated a lower mortality rate (OR: 0.52, 95% CI: 0.29–0.92, P = 0.023) among hypoalbuminemia patients who received albumin infusion compared to those who did not." (PMID 39048942, 2024). "Ionic calcium values are not affected by albumin concentration, whereas total plasma calcium decreases with hypoalbuminemia and increases in hyperalbuminemia." (PMID 38791683, 2024). "For ALB, another important hematological indicator affecting VPA drug concentration, patients with hypoalbuminemia (below 35 g/L) may have significantly-increased free VPA concentrations." (PMID 39744128, 2024). "In this review, three of the five studies analyzing albumin found a significant difference in nonunion rates for patients with hypoalbuminemia." (PMID 39518692, 2024). "Although 90% of cisplatin binds to serum albumin, theoretically reducing its free concentration and nephrotoxicity, the specific relationship between hypoalbuminemia and CIA has not been comprehensively evaluated." (PMID 39723253, 2024). "Although not statistically significant, the percentage of albumin showed a weak negative correlation with uNGAL, confirming that hypoalbuminemia can be related to or intensified by proteinuria." (PMID 39897361, 2024). "The possible explanation of lower serum albumin in HD could be due to higher inflammation in the form of increased hs-CRP in HD as compared to CAPD, which could have led to more pronounced hypoalbuminemia in the HD group." (PMID 39411605, 2024). "In conclusion, this descriptive review of HDMTX courses in the treatment of children with ALL has shown that hypoalbuminemia is a frequent occurrence when therapy with ASP is ongoing, and that it has a significant impact on MTX pharmacokinetics, depending on the degree of albumin suppression." (PMID 39305296, 2024). "In general, patients with high ferritin levels and chronic inflammation are expected to have low serum albumin levels, and hypoalbuminemia is considered a negative prognostic factor in many diseases." (PMID 37432308, 2023). "Blood tests showed that presence of hypoalbuminemia was more prevalent in this group of patients (32.1% vs. 8.6%), and that albumin levels were lower, but without clinical significance (36.2 g/L vs. 39 g/L)." (PMID 38201841, 2023). "The values of serum albumin measured by BCG are about 5.5 g/L higher than those measured by the BCP, CE, or iMN methods, so the definition of the degree of hypoalbuminemia required to meet a definition of NS varies according to the method used for quantifying serum albumin concentration." (PMID 36269406, 2023).
Hypoalbuminemia (continued). "The severity of hypoalbuminemia is believed to be a surrogate marker for the degree of imbalance in prothrombotic and antithrombotic factors, although VTE can occur even when the serum albumin is only moderately reduced." (PMID 37680313, 2023). "Although LOS (mean +SD) in the hypoalbuminemia group was higher than that in the normal group, their data revealed statistically that increased serum albumin levels did not shorten LOS or decrease clinical mortality." (PMID 36827460, 2023). "Among the 42 patients without HRS, 69% (n=29) had hypoalbuminemia (mean value=2.67 g/dL), and the remaining had normal serum albumin levels." (PMID 38034151, 2023). "The result is similar to the present study, which showed that there was a lower mortality among patients with an albumin infusion compared to patients without an albumin infusion (OR: 0.52, 95% CI: 0.29–0.92) for hypoalbuminemia patients with SAP." (PMID 37277756, 2023). "In the present study, the high NLR group had low albumin level and albumin level was not a predictor of relapse in the univariate analysis using the cox proportional hazards model, and there were no cases of hypoalbuminemia in the blood tests." (PMID 36634124, 2023). "Thus, for patients with hypoalbuminemia undergoing HIPEC, preoperative nutrition support with monitoring of albumin level should be necessary." (PMID 36814253, 2023). "Hypoalbuminemia can develop during acute stress, major operations, trauma, or infection and does not always require albumin replacement." (PMID 37432160, 2023). "The PSM analysis demonstrated that mortality (OR: 0.52, 95% CI: 0.29–0.92, P = 0.023) was less common in albumin-infused than non-albumin-infused hypoalbuminemia patients." (PMID 37277756, 2023). "As previous studies have shown that healthy older people have normal albumin levels, age in itself is not a pathophysiological mechanism for hypoalbuminemia." (PMID 36776614, 2023). "After discharge, laboratory tests were performed at an outpatient clinic for 2 months at 2-week intervals, and proteinuria and hypoalbuminemia (serum albumin 1.5 g/dL) still did not improve." (PMID 37241051, 2023). "The CRP to albumin ratio (high CRP and hypoalbuminemia), reflecting prolonged exhaustion owing to inflammation, may be a potential prognostic factor in patients with cancer." (PMID 37073452, 2023). "At the time of discharge, hypoalbuminemia (serum albumin 1.7 g/dL) and general edema had not improved." (PMID 37241051, 2023). "Serum albumin levels decrease with age by approx. 0.1 g/L per year; however, age on its own is not a reason for hypoalbuminaemia." (PMID 37111024, 2023). "33% of the patients had hypoalbuminemia (serum albumin <3.5 g/dl), while 67% of the patients had normal albumin levels (3.5-5.5 g/dl)." (PMID 38249181, 2023). "In our study, patients with fungal infections seemed to have lower albumin levels on admission to a degree of hypoalbuminemia, although a non-statistically significant lower BMI was in the range of overweight." (PMID 36012869, 2022). "The ratios of saline to albumin were not reported in the post hoc publication on the role of baseline hypoalbuminemia in SAFE and are therefore shown here." (PMID 36430652, 2022). "Hypoalbuminemia was not prevented in nephritic megalin–cubilin KO mice, perhaps as reabsorbed albumin undergoes proteolysis." (PMID 36139492, 2022). "The observed predictive role of high globulin cannot be merely explained by low albumin because of the significant survival difference between groups A and B, both of which did not have hypoalbuminemia." (PMID 35889807, 2022). "No instances of hypoalbuminemia were observed in our study and all included patients exhibited serum albumin levels within the normal range before the first apheresis treatment." (PMID 35842435, 2022). "Albumin is a negative acute phase protein, and hypoalbuminemia is a maker of a heightened inflammatory state of the patient." (PMID 36615064, 2022).
Hypoalbuminemia (continued). "This study confirms that hypoproteinemia and hypoalbuminemia are infrequently observed in cats with CE and that albumin and SPE fraction levels are not correlated with the severity of the disease." (PMID 36136669, 2022). "There were significant statistical differences in preoperative laboratory tests, including red blood cells, PT, albumin, globulin, A/G ratio (P < 0.05) between with and without postoperative hypoalbuminemia patients." (PMID 34996896, 2022). "Considering the SAFE study results, we did not routinely infuse commercially available albumin for the correction of hypoalbuminemia during CRRT." (PMID 35672868, 2022). "We also found that patients receiving the ERAS care had a lower rate of severe postoperative hypoalbuminemia without increasing the albumin transfusion." (PMID 35331289, 2022). "The patients were divided into hypoalbuminemia (< 35 g/L) and non-hypoalbuminemia group (≥ 35 g/L) based on postoperative albumin levels." (PMID 34996896, 2022). "Our study found a significant difference in albumin levels between the surviving and dying groups, but hypoalbuminemia was not a prognostic influence in this study." (PMID 36225233, 2022). "A further consequence of hypoalbuminemia was the faster clearance of OTA from hepatocytes by canalicular secretion, which may be explained by reduced albumin-mediated intracellular retention of OTA." (PMID 35962801, 2022). "Hypoalbuminemia was common in the PJP patients (only two of the patients did not have serum albumin levels measured during PJP)." (PMID 36552932, 2022). "In our study, the albumin levels of the patients were all in the normal range, and none of the patients had hypoalbuminemia." (PMID 35188060, 2022). "Absolute concentrations of albumin were not determined, leaving modest hypoalbuminemia as the most likely explanation for slightly elevated ΔS-Cys-Albumin in the cancer patients relative to controls." (PMID 36182099, 2022). "If hypoalbuminemia is an effect moderator, the crystalloid-to-albumin ratio of fluid resuscitation volumes is not well characterized." (PMID 36430652, 2022). "Although HbA1c levels are affected by a variety of CKD conditions, the alternative markers of glycated albumin and fructosamine are also influenced by hypoalbuminemia and have not been adequately validated in CKD populations." (PMID 36009406, 2022). "The fact that the hypoalbuminemia patients had a higher mortality also in the non-cancer population (47% vs. 14%) is another demonstration that albumin is an independent predictor of disease severity." (PMID 35268297, 2022). "Researchers who oppose the use of exogenous albumin insisted that hypoalbuminemia is not a modifiable factor that can improve postoperative outcomes, but a result of poor prognosis after pancreatectomy." (PMID 35160076, 2022). "In terms of albumin levels, it is widely accepted that patients with hypoalbuminemia do not recover easily; however, there is currently no data to directly verify the relationship between albumin level and prognosis of patients with MDA5+DM." (PMID 34692722, 2021). "Although hypoalbuminemia seems to predict a poor prognosis, infusion of albumin has not been confirmed to be an effective therapy to improve mortality in septic patients." (PMID 34399809, 2021). "The level of ALB in the therapy group was higher than that of the control group, suggesting that the combination of western medicine and TCM in the therapy group has a better effect on the improvement of hypoalbuminemia (∗p < 0.05)." (PMID 34840588, 2021). "Interestingly, the significant correlation between serum albumin and both AFOP and areas of normal lung corroborates the likely link between hypoalbuminemia and alterations of endothelial permeability." (PMID 34903264, 2021). "The albumin concentration in canine CPP is significantly higher than in FFP, suggesting that it may be a possible treatment for hypoalbuminemia in dogs while avoiding volume overload." (PMID 34277747, 2021).